SLC2A9 (solute carrier family 2 member 9)
Diseases named in the same sentence as SLC2A9 in open-access papers (continued):
Sharing a sentence is not in itself a finding about the gene and the disease.
renal disease (3 papers, 2013 to 2024). "Solute carrier protein 2 family, member 9 (SLC2A9) SNPs (chromosome 4) associated with cardiovascular or renal disease risk factors." (PMID 24379826, 2013). "In addition, we found suggestive association between SLC2A9 SNPs and the renal disease development marker UACR." (PMID 24379826, 2013). "In summary, our GWAS extends and confirms the association of SLC2A9 with SUA for the first time in a Mexican American cohort and also shows for the first time its association with cardiovascular-renal disease risk factors." (PMID 24379826, 2013).
tumor (3 papers, 2015 to 2022). "Additionally, lower levels of SLC2A3, SLC2A6, SLC2A9, SLC2A12, and SLC2A14 and higher levels of SLC2A1, SLC2A5, SLC2A10, and SLC2A11 had an association with advanced tumor stage." (PMID 36518662, 2022). "More typically, hypouricemia is associated with high fractional excretion of uric acid due to genetic causes; including mutations in genes such as SLC22A12 (URAT1) and SLC2A9 (GLUT9) or factors such as uricosuric usage, renal tubulopathy, neoplasias, and other conditions." (PMID 29904633, 2018). "LUAD tumor tissues showed higher mRNA expressions of SLC2A1, SLC2A5, and SLC2A12 and lower expressions of SLC2A3, SLC2A4, SLC2A6, SLC2A9, and SLC2A14." (PMID 36518662, 2022). "A lower differentiation grade tumor is implied by overexpression of SLC2A1, SLC2A5, SLC2A10, SLC2A11and lower levels of SLC2A3, SLC2A6, SLC2A9, SLC2A12, and SLC2A14, emphasizing the possibility of these molecular roles for predicting the course of the tumor." (PMID 36518662, 2022). "In our study, we show that transcriptional levels of SLC2A1, SLC2A5 are upregulated and those of SLC2A3, SLC2A6, SLC2A9, SLC2A14 are downregulated in LUAD patients, supporting the role of SLC2A1, SLC2A5 as oncogenes and SLC2A3, SLC2A6, SLC2A9, SLC2A14 as tumor suppressor genes." (PMID 36518662, 2022). "Furthermore, SLC2A3, SLC2A6, SLC2A9, SLC2A12, and SLC2A14 levels were lower in patients with advanced tumor stages, suggesting that these genes might act as a barrier to the progression of LUAD." (PMID 36518662, 2022).
neurodegenerative disease (2 papers, 2019 to 2021). A disorder of the central nervous system characterized by gradual and progressive loss of neural tissue and neurologic function. "Variation in both SUA and the SLC2A9 gene have several intriguing associations with human cognition and neurodegenerative disease." (PMID 31695625, 2019). "Variations in SLC2A9 gene, encoding the urate transporter GLUT9, are closely related to human cognition and neurodegenerative diseases." (PMID 34335246, 2021).
neurological disorders (1 paper, 2011). "In summary, this study characterized epistasis signals in SUA levels in the MICROS population and shows that SLC2A9 may be an important epistatic locus interacting with multiple loci across the genome, including those with neuronal influence and/or associating with neurological disorders." (PMID 21886828, 2011).
psychiatric disorder (1 paper, 2013). A disorder characterized by behavioral and/or psychological abnormalities, often accompanied by physical symptoms. "Crude and adjusted logistic regression analysis of SLC2A9 rs6855911 and psychiatric disorders according to sex." (PMID 24204615, 2013).
SLC2A9 also shares sentences with these, for which no sentence is quoted: Insulin resistance (3 papers); ischaemic heart disease (3); endothelial dysfunction (2); Hypercholesterolemia (2); Hyperglycemia (2); Hyperinsulinemia (2); kidney damage (2); osteoporosis (2); urolithiasis (2); aging (1); arteriosclerosis (1); cardiovascular diseases (1); ciliopathies (1); colorectal cancer (1); COVID-19 (1); cystic kidney disease (1); essential hypertension (1); genetic disorders (1); glioblastoma (1); glucosuria (1); hereditary renal hypouricemia (1); hyperlipidemia (1); hyperparathyroidism (1); ischemia (1); ischemic stroke (1); kidney failure (1); leukemia (1); liver cancer (1); lung carcinoma (1); memory impairment (1).
A further 11 diseases each share a sentence with SLC2A9 in 1 paper.